NDRG2 (NDRG family member 2)
Diseases named in the same sentence as NDRG2 in open-access papers (continued):
Sharing a sentence is not in itself a finding about the gene and the disease.
breast carcinoma (continued). "TCGA data analysis of basal and triple-negative types of human breast cancers revealed a significant negative correlation between NDRG2 and PD-L1 expression, which was, again, confirmed by regression analysis using multiple human TNBC cell lines." (PMID 34885221, 2021). "Nevertheless, studies evaluating the putative tumor suppressive biological and clinical impact of NDRG2 were irrespective of intrinsic breast cancer subtypes or mainly focused on luminal or basal B breast cancer cell models in vitro and in vivo." (PMID 27400234, 2016). "In more detail, stratification of breast cancer specimen in triple negative (n = 24), luminal-type (n = 87) and HER2-enriched (n = 27) breast cancers showed a pronounced downregulation of NDRG2 in luminal-type and HER2-enriched tumors (P<0.001) compared to triple negative cancers (P = 0.025)." (PMID 27400234, 2016). "In summary, we provide for the first time clinical and functional evidence that the described putative tumor suppressive function of NDRG2 may be confined to luminal-type and basal B-type (more reflecting mesenchymal TNBC) breast cancers." (PMID 27400234, 2016). "Thus, NDRG2 contributes to the genesis and progression of OSCC and breast cancer partly through the inhibition of PI3K/Akt signaling." (PMID 26506239, 2016). "Interestingly, NDRG2 downregulation was abundantly found in luminal A, luminal B and HER2-enriched breast cancer while TNBC (own tissue collective, St." (PMID 27400234, 2016). "NDRG2 also suppresses matrix metalloproteinase-9 (MMP-9) expression through the induction of BMP-4 secretion and inhibits NF-kappaB activity and MMP-2 and -9 secretion, which abrogates the metastatic potential of breast cancer and fibrosarcoma cells." (PMID 25061501, 2014). "Whether hypoxia-inducible factors are involved in NDRG2-mediated GLUT1 content and glucose intake regulation in breast cancer needs to be directly determined in future studies." (PMID 24636131, 2014). "NDRG2 inhibited glucose uptake by promoting GLUT1 protein degradation without affecting GLUT1 transcription in both breast cancer cells and xenograft tumours." (PMID 24636131, 2014). "Similarly, we identified the degree of correlation between NDRG2 expression and GLUT1 expression in 269 breast cancer specimens." (PMID 24636131, 2014). "Furthermore, we used quantitative real-time RT-PCR to quantify the levels of NDRG2 and MYC mRNA in thyroid gland cancer and breast cancer, using a distinct set of normal and tumor samples." (PMID 21226903, 2011). "The function of NDRG2 in breast cancer has not been studied as extensively as NDRG1." (PMID 38611020, 2024). "Interestingly, breast cancer cells expressing NDRG2 have also inhibited osteoclast differentiation by downregulating secreted ICAM1 expression, suggesting that NDRG2 may suppress bone metastases from breast cancer." (PMID 38611020, 2024). "NDRG2 was shown to suppress the TGF-β1-mediated induction of MMP through the regulation of integrin α3 expression in hepatocarcinoma and integrin α6 expression in metastatic murine breast cancer cells (4T1), thereby suppressing the activation of latent extracellular TGF-β." (PMID 34685629, 2021). "Both NDRG2 mRNA and protein levels were decreased in MCF-7/ADR cells compared with MCF-7 cells, indicating that NDRG2 might regulate the ADR resistance of breast cancer." (PMID 28423695, 2017). "In breast cancer cells, the specific induction of active BMP-4 is exclusively observed in breast cancer cells expressing NDRG2 but not in control breast cancer cells, and NDRG2 expression inhibits the mRNA expression of several MMPs and the gelatinolytic activity of MMP9." (PMID 26506239, 2016).
breast carcinoma (continued). "Although NDRG2 is thought to be a potential tumor suppressor in breast cancer, tumorigenesis studies investigating the tumor suppressive role of NDRG2 were irrespective of intrinsic breast cancer subtypes or mainly focused on luminal or basal B breast cancer cell models in vitro and in vivo." (PMID 27400234, 2016). "Whether this also applies to other cancers is not known, and we therefore quantified MYC and NDRG2 mRNA in a set of breast cancer samples." (PMID 21226903, 2011). "We also quantified the level of MYC in the same breast cancer samples to investigate whether or not a high level of MYC expression could be responsible for the observed NDRG2 down-regulation." (PMID 21226903, 2011). "Moreover, NDRG2 knockdown in the basal A breast cancer cell line HCC1806 caused a reduced proliferation and migration rate while NDRG2 over-expression in basal A-like BT20 breast cancer cells, lacking endogenous NDRG2 expression, resulted in an increased cell proliferation." (PMID 27400234, 2016). "However, studies evaluating the putative tumor suppressive biological and clinical impact of NDRG2 in breast cancer were irrespective of intrinsic breast cancer subtypes or as mentioned in this study before, mainly based on luminal- and basal B-type cell models." (PMID 27400234, 2016). "There is a negative correlation between NDRG2 expression and CD24 expression in gallbladder carcinoma (GBC), HCC, breast cancer and lung adenocarcinoma." (PMID 26506239, 2016).
colorectal cancer (30 papers, 2007 to 2025). A primary or metastatic malignant neoplasm that affects the colon or rectum. "NDRG2 promoter methylation was observed to be associated with the invasiveness in gastric and colorectal cancer and with the aggressiveness of glioma tumor." (PMID 28390436, 2017). "In conclusion, NDRG2 mRNA levels were decreased in both high-risk colorectal adenoma and in colorectal carcinoma compared to corresponding normal colonic mucosa from the same individual." (PMID 17935612, 2007). "Using quantitative RT-PCR, we have determined the mRNA levels for NDRG2 in low-risk (n = 15) and high-risk adenomas (n = 57), colorectal carcinomas (n = 50) and corresponding normal tissue, as well as control tissue from healthy individuals (n = 15)." (PMID 17935612, 2007). "When comparing adenomas/carcinomas with adjacent normal tissue from the same individual, NDRG2 expression levels were significantly reduced in both high-risk adenoma (p < 0.001) and in colorectal carcinoma (p < 0.001)." (PMID 17935612, 2007). "However, in contrast, the present study together with our previous work indicated that NDRG4 and NDRG2 protein expression was both decreased in colorectal cancer and similar had association with clinicopathological characteristics and prognosis." (PMID 25749388, 2015). "Furthermore, NDRG2 expression level in colorectal carcinomas tissues was lower than that of adjacent normal tissue, while the expression pattern of c-Myc was the inverse association of NDRG2." (PMID 26317652, 2015). "Furthermore, reduced NDRG2 expression was published in high-risk adenoma, colorectal carcinoma, glioblastoma thyroid cancer, esophageal cancer renal cancer, gallbladder carcinoma and breast cancer." (PMID 23056173, 2012). "Whether down-regulation of NDRG2 in colorectal carcinoma is a cause or a consequence of malignant progression is at present unclear." (PMID 17935612, 2007). "GSK3β phosphorylation and activation by NDRG2 downregulate β-catenin in colorectal cancer (SW620) cells." (PMID 40378957, 2025). "Accumulated studies about the gene function suggest that NDRG2, also known as a tumor-suppressor gene, plays anti-proliferative and pro-apoptotic roles in many tumor issues, such as colorectal cancer, gastric cancer, hepatocellular carcinoma, etc.." (PMID 37373150, 2023). "Previous studies have revealed that NDRG2 suppresses glycolysis of colorectal carcinoma and renal cell carcinoma." (PMID 34951340, 2022). "There results were consistent with our previous study in colorectal carcinoma, in which we found that NDRG2 inhibited LDHA expression and aerobic glycolysis in colorectal carcinoma by repressing c-Myc expression." (PMID 31523182, 2019). "We first cloned NDRG2 (N-myc downstream-regulated gene 2) and verified its tumor suppressor role in multiple solid tumors, including colorectal cancer and hepatocellular carcinoma." (PMID 29445150, 2018). "Associations between tumors (including glioblastoma, gastric cancer, colorectal cancer, breast and liver cancers, meningioma, bladder and thyroid cancers) and N-myc downstream-regulated gene 2 (NDRG2) have been reported in numerous studies." (PMID 28390436, 2017). "Further investigations are necessitated to verify if NDRG2 molecule can be a therapeutic target in colorectal cancer." (PMID 29399558, 2017). "Several studies have shown NDRG2 promoter CpG island methylation and down-regulation in liver, gastric, colorectal cancers (CRC), glioblastomas and anaplastic meningioma." (PMID 28390436, 2017). "Consistent with the target molecules inhibited in NDRG2-overexpressing colorectal cancer cells, the expression of GLUT1, glycolytic pathway-related enzymes HK2, PKM2 and LDHA increased significantly in NDRG2-knockdown Caco-2, HT-29 and HCT116 cells." (PMID 26317652, 2015). "The ability of NDRG2 to inhibit glycolytic and glutaminolytic targets contributes to the repression of c-Myc, leading to inhibition of colorectal cancer cells' growth and proliferation." (PMID 26317652, 2015).
colorectal cancer (continued). "These target molecules in glucose transport and catabolism all contributed to NDRG2-induced aerobic glycolysis inhibition in colorectal cancer cells." (PMID 26317652, 2015). "In summary, this study illustrates the regulatory role and molecular mechanism of tumor suppressor NDRG2 in metabolic reprogramming of colorectal cancer." (PMID 26317652, 2015). "NDRG2 inhibited glucose consumption and lactate production, glutamine consumption and glutamate production in colorectal cancer cells." (PMID 26317652, 2015). "We propose a scheme for NDRG2-mediated glycolysis and glutaminolysis inhibition of colorectal cancer." (PMID 26317652, 2015). "To establish the role of NDRG2 in metabolic reprogramming of colorectal cancer, we used a metabolomics approach to analyze differences among the global metabolic profiles of NDRG2-overexpressing and control HCT116 cells." (PMID 26317652, 2015). "Our data demonstrate for the first time that NDRG2 inhibits glycolysis in colorectal cancer cells by inhibiting glucose transporter 1, catalytic enzymes HK2, PKM2, LDHA." (PMID 26317652, 2015). "Our current experiments demonstrate for the first time that NDRG2, which is downregulated in colorectal cancer, inhibits glycolysis and glutaminolysis in addition to inhibiting cancer cell proliferation and invasion." (PMID 26317652, 2015). "We further investigated the role of c-Myc in NDRG2-induced glycolysis and glutaminolysis inhibition in colorectal cancer cells." (PMID 26317652, 2015). "Taken together, we have identified that NDRG2 inhibited aerobic glycolysis and glutaminolysis, which were mediated by c-Myc in colorectal cancer cells." (PMID 26317652, 2015). "At first, we analyzed the expression of NDRG2 in tissue microarrays containing 68 colorectal carcinomas and adjacent normal colorectal tissues by immunohistochemistry." (PMID 26317652, 2015). "Feng and colleagues reported that downregulation of N-myc downstream-regulated gene 2 (NDRG2) expression involving promoter methylation and microRNA-650 promoted colorectal cancer progression." (PMID 23991130, 2013). "It had been proved that Ndrg2 served as a tumor suppressor gene involved in gastric cancer, colorectal cancer, hepatocellular carcinoma, esophageal squamous cell carcinoma, and thyroid cancer." (PMID 22773039, 2012). "The N-myc downstream-regulated gene 2 (NDRG2) has been recognized as a tumor suppressor gene, which is downregulated in human hepatocellular carcinoma, colorectal carcinoma and many other malignancies." (PMID 23056173, 2012). "CpG methylation in NDRG2 was detected in all cell lines and in 8 of the 30 (27%) colorectal cancer patients." (PMID 19257893, 2009). "NDRG2 mRNA levels were lower in colorectal carcinomas compared to normal tissue from the control group (p < 0.001)." (PMID 17935612, 2007). "In the Norwegian cohort, NDRG2 mRNA levels were statistically significantly reduced in colorectal carcinoma when compared to the healthy controls." (PMID 17935612, 2007). "Dividing all data collected in this study into groups of males and females showed a general lower level of NDRG2 expression in females with colorectal carcinoma (both normal and cancer tissue)." (PMID 17935612, 2007). "Similarly, targeting NDRG2 demonstrates its pro-apoptotic and anti-proliferative effects, particularly in glioblastoma and colorectal cancer." (PMID 40378957, 2025). "Additionally, NDRG2 not only facilitates colorectal cancer differentiation, but also reduces the differentiation of macrophages into tumor-associated macrophages in the tumor microenvironment." (PMID 37373150, 2023). "As a tumor suppressor, NDRG2 inhibited glycolysis and glutaminolysis in colorectal cancer cells." (PMID 31523182, 2019). "In colorectal cancer cells, we discovered that NDRG2 inhibits glycolysis and glutaminolysis." (PMID 31523182, 2019). "In addition, LDHA was significantly suppressed by NDRG2 in colorectal cancer cells and hepatocellular carcinoma cells." (PMID 31523182, 2019).
colorectal cancer (continued). "Our in-vitro model demonstrates that the NDRG2 overexpression attenuates several aspects of tumorigenesis including the proliferation and invasive potential of human colorectal cancer cell line HCT116, a widely used model for KRAS mutated colorectal cancer." (PMID 29399558, 2017). "Our data in combination with our prior publications on a KRAS mutated negative cell line point to NDRG2 as a potential therapeutic target for colorectal cancer." (PMID 29399558, 2017). "As NDRG4 is more than 60% identical in amino acid sequence to NDRG2, this sequence similarity suggests NDRG4 may recapitulate the tumor suppressive function of NDRG2 in colorectal cancer." (PMID 25749388, 2015). "In addition, the growth and proliferation of colorectal cancer cells were suppressed significantly by NDRG2 through inhibition of glycolysis and glutaminolysis." (PMID 26317652, 2015). "However, NDRG2 was shown to restrain the Wnt/TCF/beta-catenin signalling pathway and NDRG2 decreases in a tumor-stage dependent fashion in colorectal carcinoma." (PMID 23056173, 2012). "However, when comparing affected tissue from individuals with colorectal cancer to corresponding tissue from a healthy control, a statistically significant difference in the level of NDRG2 mRNA was observed (p < 0.001)." (PMID 17935612, 2007). "However, when compared to the control group of healthy individuals, only the affected tissue from individuals with colorectal carcinoma shows a statistically significant reduction in NDRG2 mRNA levels." (PMID 17935612, 2007). "Furthermore, NDRG2 expression was reduced in colorectal carcinoma compared to normal tissue from healthy individuals." (PMID 17935612, 2007). "Future studies will be needed to examine whether increased NDRG2 levels in colorectal carcinoma correlate with improved prognosis." (PMID 17935612, 2007). "However, we found that NDRG2 and NDRG4 mRNA expression was both decreased in colorectal cancer and adversely associated with clinical outcome within the same study cohort, indicating a tumor suppressive role of NDRG4 in colorectal cancer, which was similar to the role of NDRG2 in colorectal cancer." (PMID 26515606, 2016). "Here, we examined the outcome of NDRG2 overexpression on proliferation, invasion, migration and MMP activity of HCT116 colorectal cancer cell line." (PMID 29399558, 2017). "To verify the relationship between NDRG2 and the target molecules in vivo, we also investigated the expression of NDRG2 and c-Myc, β-catenin, GLUT1, HK2, PKM2, LDHA, ASCT2, GLS1 in tissues from clinical colorectal carcinomas samples." (PMID 26317652, 2015). "Recently, the crystal structure of human NDRG2 protein was resolved and NDRG2 was proposed to suppress TCF/β-catenin signaling in the tumorigenesis of human colorectal cancer via a molecular interaction." (PMID 22920753, 2012). "NDRG2 could also promote the BMP2-induced osteoblastic differentiation and calcification, as well as colorectal cancer differentiation." (PMID 37373150, 2023). "Indeed, in other tissues, overexpression of mir-650 results in more aggressive cancer such as oral cancer and colorectal cancer by targeting GFI and NDRG2, respectively." (PMID 35202088, 2022). "We initially cloned human NDRG2 (GenBankTM No. AF159092) and found it is associated with tumor differentiation, progression and prognosis in colorectal cancer." (PMID 25749388, 2015). "To further confirm that NDRG2 overexpression regulates AMPK activity in other cancer cell types, we investigated the effects of NDRG2-induced inhibition of AMPK activity in HCT116 colorectal carcinoma cells, which were previously used to show the anticancer effect of NDRG2 expression." (PMID 25061501, 2014).
colorectal cancer (continued). "Interestingly, NDRG2 in colorectal cancer could affect the complex components of ubiquitin-protein ligase E3A (UBE3A) and estrogen receptor beta (ERβ), reducing the ubiquitin-mediated proteasome degradation of ERβ, demonstrating that NDRG2 could bind to UBE3A to hinder the binding of UBE3A to ERβ." (PMID 34885221, 2021).